LCN2 (lipocalin 2)
Diseases named in the same sentence as LCN2 in open-access papers (continued):
Sharing a sentence is not in itself a finding about the gene and the disease.
tumor (continued). "The role of LCN2 in the progression of tumors is dependent mainly on the type of tumor." (PMID 40109857, 2025). "Conditioned medium from LCN2-high tumor cells cocultured with astrocytes significantly enhanced macrophage migration, whereas conditioned media from LCN2-overexpressing tumor cells alone or cocultured with oligodendrocytes had no such effect." (PMID 41436606, 2025). "LCN2 is a regulator of angiogenesis during tumor progression." (PMID 40109857, 2025). "Our research group reported that Serpin family A member 3 (SERPINA3) and Lipocalin2 (LCN2), which are upregulated in PCa and modulated by osteoblast-derived EVs, regulate PCa cell proliferation and invasion in a tumor-suppressive manner, supported by in vitro and in vivo models." (PMID 41465584, 2025). "The roles of LCN2 in tumor biology are not fully understood." (PMID 40109857, 2025). "To further examine whether astrocytes mediate LCN2-driven macrophage recruitment, we assessed macrophage migration via conditioned media from cocultures of tumor cells and astrocytes." (PMID 41436606, 2025). "The functions of LCN2 appear to be highly tumor- and tissue-specific." (PMID 41303420, 2025). "Moreover, LCN2 is frequently upregulated in diverse cancers and has been linked to EMT, invasion, angiogenesis, and modulation of the tumor microenvironment, including interactions with myeloid cells and neutrophils." (PMID 41190142, 2025). "Moreover, IHC staining of the xenograft tumor samples also showed that LCN2 overexpression reduced SPARC protein levels." (PMID 39424639, 2024). "Once recruited and activated by brain metastasizing cells, reactive astrocytes induce growth-promoting signaling in tumor cells by expressing PD-L1 to inhibit T-cell activation and secrete inflammatory factors, including lipocalin-2, directly suppressing immune cells." (PMID 39188682, 2024). "Moreover, high LCN2 expression correlated with smaller tumor sizes (p = 0.0038), fewer distant metastases (p = 0.0139), and LN metastases (p = 0.002)." (PMID 39424639, 2024). "Importantly, SPARC knockdown partially reversed the tumor-promoting effect induced by LCN2 knockdown." (PMID 39424639, 2024). "In this study, we demonstrated that LCN2 was aberrantly expressed in GC and negatively correlated with tumor grade and poor prognosis in patients with GC by combining the results of our previous scRNA-seq analysis data with information from database and our clinical cohort." (PMID 39424639, 2024). "Furthermore, overexpression of LCN2 induces epithelial-mesenchymal transition in PCa, promoting tumor metastasis." (PMID 38694500, 2024). "In nude mice, LCN2 overexpression in MGC803 cells (MGC-803-LCN2) reduced tumor volume and weight." (PMID 39424639, 2024). "In addition to expressing transferrin receptors, TAMs also supply tumor cells with iron through the secreted LCN2." (PMID 39850877, 2024). "For instance, few studies reported that LCN2 could promote cancer growth while others suggested LCN2 as a tumor suppressor." (PMID 39424639, 2024). "In mouse models of IBC, LCN2 depletion reduced tumor growth, skin invasion, and brain metastasis." (PMID 39040042, 2024). "Moreover, LCN2 has been found to influence tumor progression by regulating various intracellular signaling pathways." (PMID 39424639, 2024). "MMP-9 localized levels may rise as a result of increased LCN2 expression in tumor cells or invading inflammatory cells." (PMID 39040042, 2024). "The tumor microenvironment (TME) is a critical source for factors like hypoxia (HIF-1α, NO), and signaling proteins derived from cells such as cancer-associated fibroblasts and macrophages (TGFβ, LCN2, IL-6, IL-1β, etc.)that influence EMT50." (PMID 39737957, 2024). "Consequently, understanding the role of LCN2 in primary tumor growth and invasion is vital for developing targeted therapies to prevent BCBM." (PMID 39188682, 2024).
tumor (continued). "This suggests a promising translational pathway for future CRC therapies, particularly in patients with advanced Tumor Node Metastasis (TNM) stages or metastasis who might benefit from targeted LCN2 suppression to limit cancer spread." (PMID 39839775, 2024). "However, the basic form of LCN2 is a secreted protein, and a recent study also reported the role and mechanism of LCN2 as secreted protein in tumor progression." (PMID 39424639, 2024). "And previous research had proved that endoplasmic reticulum stress (ER stress) may also be involved in the role of macrophages in iron metabolism in the tumor microenvironment by upregulating LCN2 expression." (PMID 39850877, 2024). "Thereafter, the anti-Lcn2 component of the anti-tumor T cell response could then be boosted by late vaccination with VSV-IFNß-Lcn2." (PMID 38045348, 2023). "INHBA and LCN2 were downregulated in this study, which implied that INHBA and LCN2 may play crucial roles in tumor recurrence in HCC patients after LT." (PMID 37089051, 2023). "However, the literature on the tumor-suppressive function of Lcn-2 is limited, and less frequently reported." (PMID 37958332, 2023). "Furthermore, LCN2 promotes tumor metastasis through the epithelial–mesenchymal transition in breast and prostate cancers." (PMID 38072118, 2023). "In order to verify whether the iron excreted by LCN2 was beneficial to tumor progression, we treated the CRC cell line HCT116 with FC or DFO, and cell proliferation was detected by CFSE staining using flow cytometry." (PMID 38072118, 2023). "LCN2 promotes tumor development by affecting cell proliferation, apoptosis, and migration." (PMID 38072118, 2023). "Collectively, these results indicated that LCN2 promoted tumor metastasis." (PMID 38072118, 2023). "With the promising in vitro results above, we finally evaluated whether this RNAi nanoplatform could effectively deliver siRNA into tumor tissues to silence LCN2 expression and inhibit tumor progression." (PMID 36899380, 2023). "This may be due to the small number of animals, but as a trend study, it has been well documented that inhibiting LCN2 expression successfully suppressed OSCC tumor proliferation and metastasis and could be a potential target for OSCC treatment." (PMID 36899380, 2023). "The better anticancer effect of NPs-siLCN2 was further demonstrated by histological analysis, in which the NPs were the most effective in inhibiting tumor proliferation, silencing LCN2 expression, and suppressing p-EGFR and Ki67 expression in the tumor tissues." (PMID 36899380, 2023). "Although LCN2 has been confirmed to be upregulated in a variety of tumors, and has the potential to affect tumor progression by affecting processes such as cell proliferation, apoptosis, and migration, the functions of LCN2 in tumor-infiltrating T cells require clarification." (PMID 38072118, 2023). "Moreover, Alistipes, a possible pathogen, is implicated in the pathogenesis, which thrives in an inflammatory environment devoid of lipocalin 2, encouraging inflammation and tumor development." (PMID 38144468, 2023). "Lastly, LCN2 released from neutrophils significantly enhanced the stemness of tumor cells." (PMID 37174093, 2023). "However, recent studies showed that Lcn-2 can have both a pro- and anti-tumorigenic role depending on the tumor stage, type, and location." (PMID 37958332, 2023). "Furthermore, patients in stages II and III were reported to have increased expression of Lcn-2 in the tumor stroma, compared to healthy tissue, and patients with metastatic breast cancer were reported to have increased expression of Lcn-2 in the urine." (PMID 37958332, 2023). "Compared with the control group, LCN2 promoted ESCC tumour growth in vivo." (PMID 37753805, 2023).
tumor (continued). "Considering that growth of tumour cells in vivo occurs in a three‐dimensional environment, 3D cell culture showed that the LCN2/LOXL2/MMP9 ternary complex degraded the extracellular matrix by promoting the formation and extension of filopodia, thereby enhancing the invasion of tumour cells." (PMID 37753805, 2023). "Besides metabolic disorders, lipocalin-2 also has a role in a variety of cancers, and tumor-promoting functions such as increased cell proliferation and reduced apoptosis have been described." (PMID 37189804, 2023). "Most LCN2 research has focused on tumor cells; although a few studies have reported its expression and functions in other immune cells such as macrophages, its involvement in T cells remains unclear." (PMID 38072118, 2023). "In addition to iron transport, and its effects on lymphocyte apoptosis and tumor cell proliferation, the relative quantitative proteomic study of the LCN2-overexpressed cell line showed other functions of LCN2 in CRC." (PMID 38072118, 2023). "As an important iron transporter, LCN2 has been reported to be upregulated in cancer cells and to promote tumor growth by regulating cellular iron accumulation, and knocking down LCN2 has been shown to inhibit cell proliferation and reduce the cellular iron level." (PMID 37080959, 2023). "In addition to the cytokines involved in the EMT, cell proliferation, and metabolism, a major factor identified as being secreted from the stromal cells was lipocalin 2 (LCN2), which is involved in tumor progression and metastasis." (PMID 36768435, 2023). "Herein we proved this hypothesis and found that CUDC-907 displayed anti-tumor effects by downregulating LCN2 to activate ROS-IRE1α-JNK mediated autophagy." (PMID 35989326, 2022). "In addition, we suggested a new mechanism of LCN2 in the tumor microenvironment through which IL-6, a powerful cytokine in CAC, is able to specifically increase LCN2 promoter activity under control of NF-kB activation." (PMID 35470375, 2022). "Inflammation in liver tissues may bring about higher CCL20 and LCN2; further production of them by tumor cells would be the main source in HCC sera." (PMID 35308139, 2022). "Furthermore, some tumor-promoting neutrophils released lipocalin 2 (LCN2) protein activated by STAT3 to induce tumor metastatic growth." (PMID 35719975, 2022). "Both MMP7 and LCN2 are critical for cell migration, tumor invasion, and metastasis." (PMID 36551599, 2022). "The overexpression of LCN2 and MMP9 was consistently associated with the early promoter methylation status of both genes that have been found to be partially methylated in most tumor types." (PMID 36211450, 2022). "Moreover, in another study, five LM+ patients were analyzed by single-cell RNA sequencing, which showed that tumor cells (in the CSF) expressed the iron-binding protein lipocalin-2 (LCN2) and its receptor SCL22A17." (PMID 35053611, 2022). "Studies have found that the immunosuppressive chemokine CCL2 produced by tumor cells induces the autocrine secretion of lipocalin 2 (LCN2) and cooperatively generates immunoregulatory DCs (regDCs) with decreased HLA-DR expression and increased PD-L1 expression." (PMID 36505406, 2022). "Lipocalin-2 (Lcn2), also denoted as neutrophil-gelatinase-associated lipocalin (NGAL), is a transporter protein related to energy homeostasis, inflammatory response, tumorigenesis, and tumor growth." (PMID 35701840, 2022). "Furthermore, multivariate analysis revealed that LCN2 low expression status was a significant adverse prognostic factor for overall survival of GC patients (p = 0.04), as well as tumor invasion and lymph node metastasis." (PMID 35705840, 2022). "LCN2 contributes to survival and cancer development in the tumor microenvironment." (PMID 35470375, 2022). "Although the mechanisms by which LCN2 regulates tumor progression in IGC are still unclear, LCN2 may be a potential molecular marker to monitor the transition from epithelial phenotype to EMT phenotype in IGC." (PMID 35705840, 2022).
tumor (continued). "LCN2 seems to mediate tumorigenesis by facilitating tumor invasiveness." (PMID 33799862, 2021). "However, correlating FPN (middle and right) and Lcn-2 (middle and right) expression to tumor parameters, only Lcn-2 showed a significant correlation to tumor onset (middle) as well as the number of lung metastases (right)." (PMID 33808732, 2021). "In addition, upregulated LCN2 expression led to decreased tumor malignant potential, proliferation, invasiveness, and migration ability through upregulation of the ERK signaling pathway." (PMID 34062746, 2021). "while Targeting Lcn2 iron secretion for inhibition could starve cancer cells of iron, being a potential therapy to reduce tumor growth." (PMID 33986740, 2021). "The upregulation of Lcn2 significantly increases the iron concentration at metastatic tumor stages." (PMID 33986740, 2021). "Interestingly, Lcn-2−/− TAM sequestered iron, which, in turn, favors low iron availability in the TME of Lcn-2−/− PyMT tumors and less tumor growth." (PMID 33808732, 2021). "Constitutive activation of EGFR is widely known as an instigator of tumor cells proliferation, growth, survival, and migration, which is why it is speculated that the inhibition of LCN2 in this context could serve as a therapeutical target." (PMID 33799862, 2021). "To corroborate this hypothesis, we observed a significant correlation between SLC7A11 expression and the amount of iron-loaded Lcn-2 in tumor tissue of ccRCC patients." (PMID 34069743, 2021). "However, MΦ-expressed FPN and Lcn-2 are significantly elevated in tumor tissue compared to healthy breast tissue, but only Lcn-2 was significantly associated with tumor onset, metastasis as well as recurrence." (PMID 33808732, 2021). "We hypothesize that Lcn-2-dependent changes in tumor cell metabolism might account for the observed adaptations in growth." (PMID 33808732, 2021). "To prove our hypothesis that Lcn-2 is present in tumor EC fluids, we analyzed the Lcn-2 protein content in wildtype EC fluids by ELISA and quantified Lcn-2-bound iron via AAS after the immunoprecipitation of Lcn-2 in EC fluids." (PMID 33808732, 2021). "Finally, RNA sequencing of circulating neutrophils of sham and tumor-bearing mice demonstrated a significant increase in Lcn2 transcripts of cachectic mice." (PMID 33824339, 2021). "LCN2 has also been shown to promote tumor progression in xenograft mouse models." (PMID 34342930, 2021). "Another group showed that injection of wild‐type PyMT tumor cells into LCN2‐deficient mice did not alter primary tumor formation but did significantly reduce lung metastasis." (PMID 34342930, 2021). "Silencing of LCN2 reduced tumor volumes (P = 0.0037) and tumor latency, that is, the ability to initiate tumor growth: mice transplanted with SUM149 LCN2‐silenced cells took longer to initiate tumors than did those transplanted with SUM149 control cells (P = 0.0145)." (PMID 34342930, 2021). "Moreover, TAM isolated from Lcn-2−/− PyMT tumors confirmed enhanced iron storage, which was correlated with reduced tumor growth and decreased lung metastasis." (PMID 33808732, 2021). "Moreover, LCN2-KO using CRISPR/Cas 9 gene editing technology decreases tumor cell proliferation and migration, thereby enhancing cisplatin-induced apoptosis in the human prostate cancer cell line." (PMID 34903175, 2021). "As the MMPs are upregulated by LCN2 itself as well as by other players of the tumor microenvironment such as the CXC motif chemokines, the LCN2 mediated suppression of Akt could not impede the invasion and metastasis of cancer cells." (PMID 34588926, 2021). "Moreover, PRMT1 inhibition by DCPT1061 not only inhibited tumor growth but also sensitized ccRCC to sunitinib treatment in vivo by attenuating sunitinib-induced upregulation of LCN2-AKT-RB signaling." (PMID 33859753, 2021). "Similarly, Lcn2-KO tumor-bearing mice had a significantly increased inguinal fat pad mass at the end of the study when normalizing to sham controls." (PMID 33824339, 2021).
tumor (continued). "Our data suggest a pivotal role of Lcn-2 in tumor iron-management, affecting tumor growth." (PMID 33808732, 2021). "Using this bone marrow transplantation (BMT) method, we regularly achieve high levels of chimerism (>80%) as indicated by GFP expression in circulating immune cells in both genotypes (WT and Lcn2-KO) and experimental groups (sham operation and tumor implantation)." (PMID 33824339, 2021). "Hence, the release of these pro-inflammatory cytokines from the regulatory T cells of the tumor microenvironment directly upregulates the expression and levels of LCN2 in the cancer cells." (PMID 34588926, 2021). "Taking our previous work regarding the role of MΦ as cellular source of iron within the TME and the role of both FPN and Lcn-2 in determining the MΦ iron-release phenotype into account, we aimed at clarifying the role of stromal FPN and Lcn-2 for tumor progression." (PMID 33808732, 2021). "Lipocalin-2 has an important role in tumor progression, invasion, and metastasis." (PMID 33542838, 2021). "More recently, alternative mechanisms of iron acquisition by tumor cells have been described; lipocalin-2 is a secreted protein that binds iron-loaded siderophores and can thus serve as an iron delivery vehicle upon internalization mediated by its receptor, LCN2R." (PMID 33804198, 2021). "Consistent with our in vitro observations, NUPR1-knockdown (NUPR1KD) or LCN2-knockdown (LCN21KD) PANC1 cells were more sensitive to IKE-induced tumor suppression compared to control groups in vivo, in a model in which immunodeficient mice were bearing human PDAC cells." (PMID 33510144, 2021). "Moreover, more studies are required to define how Lcn-2-bound iron is recycled within tumor cells and which downstream signaling pathways as well as metabolic signatures are fostered upon the uptake of iron-loaded Lcn-2." (PMID 33808732, 2021). "Indeed, circulating levels of LCN2 are significantly reduced in both Myd88 and Il-6 knockout tumor-bearing mice." (PMID 33824339, 2021). "With regard to the role of iron-loaded Lcn-2 in promoting pro-tumor characteristics, we performed rescue experiments applying recombinant iron-loaded (holo)-Lcn-2 (1 μg/mL, 24 h) to Lcn-2−/− tumor cells, whereby proliferation, migration, and matrix adhesion was induced." (PMID 33808732, 2021). "Future prospective studies focusing on LCN2 expression and tumor immune microenvironment could be helpful in giving a definitive answer, thus providing an immuno-based anti-cancer strategy." (PMID 33425761, 2020). "Our findings suggest that the recruitment of PMN-MDSC and the increased expression of LCN2 might contribute to the enhanced immune suppressive tumor microenvironment thus aggravate cancer progression." (PMID 32153594, 2020). "We provide new insights into the pro-tumour function of LCN-2." (PMID 31772326, 2020). "In summary, whereas the studies discussed in this section suggest that LCN2 may play a role as a tumor suppressor, most in vitro and in vivo studies in the literature support the role of LCN2 as a tumor promoter." (PMID 32575507, 2020). "However, since LCN-2 is a secreted protein, the possibility exists that iron-loaded LCN-2 is rapidly captured by tumour cells due to the enhanced expression of SLC22A17, the LCN-2 receptor." (PMID 31772326, 2020). "On balance, tumor tissue had a higher LCN2 expression level compared with that in normal tissue." (PMID 33425761, 2020). "The correlation between LCN2 expression and tumor immune infiltration was explored via TIMER, and we utilized CIBERSORT and ESTIMATE computational methods to assess the proportion of tumor-infiltrating immune cells (TIICs) and the amount of stromal and immune components from TCGA database." (PMID 33425761, 2020). "In THCA, LCN2 expression negatively correlated with tumor purity(r = −0.099, P =2." (PMID 33425761, 2020).